CD4 (CD4 molecule)
Diseases named in the same sentence as CD4 in open-access papers (continued):
Sharing a sentence is not in itself a finding about the gene and the disease.
tumor (continued). "Additionally, our data show that vascular ephrinB2 loss combined with RT enhanced systemic CD4+ and CD8+ T cell activation, trended towards decreased Treg immunosuppression, and reduced CD4+ T cell entry into the tumor." (PMID 39091728, 2024). "Overlapping or multiepitope peptide sequences recognized by both CD8+ and CD4+ T cells may help to overcome challenges like tumor heterogeneity, tumor antigen downregulation, and varied HLA haplotypes." (PMID 38314087, 2024). "In addition, the absolute numbers of infiltrating CD3+, CD4+, and CD8+ T cell populations within the UTUC tumor were inversely associated with serum Apo-A1 levels." (PMID 38534755, 2024). "Importantly, IT mPH-762 also increased the overall percentage of CD45+ TILs, CD8+ and CD4+ T cells in the tumor." (PMID 39697325, 2024). "We anticipate that patients who respond to treatment with NSC-CRAd-S-pk7 will show evidence of anti-tumor immune responses, including activation and infiltration of CD4+ and CD8+ T-cells, natural killer cells, reduced Tregs and a polarization of macrophages towards an anti-tumor phenotypic state." (PMID 39768430, 2024). "The CD4+ T cells are indirectly involved in tumor cell killing via several mechanisms." (PMID 39081320, 2024). "Furthermore, pathways involved in polyamine biosynthesis have been reported to remodel the tumor immune microenvironment by altering the activation and proliferation of CD4+ and CD8+ T lymphocytes." (PMID 39376571, 2024). "In addition, the anti-CD4CAR expressing CD8-LVs were capable of eliminating the malignant CD4 T cells in the tumor bearing mAITL mouse model and increasing their survival." (PMID 39272178, 2024). "An increased number of naïve CD4 + T helper cells may lead to enhanced immune surveillance and potential anti-tumor responses once these cells differentiate into functional T helper subsets." (PMID 39402682, 2024). "In CTCL, the tumor cells are derived from CD4 (+) CD45RO (+) T memory cells." (PMID 38540417, 2024). "Interestingly, a reduction in tumor-infiltrating CD4+ T cells and an increase in tumor-infiltrating CD8+ T cells were observed in the combination group, as seen by the significant decrease of the CD4+/CD8+ ratio." (PMID 38170044, 2024). "CD4+ T cells support the anti-tumor activity of CD8+ T cells, while Treg cells can suppress it." (PMID 39518128, 2024). "Next, we used CD4+ T/CD8+ T/NK cell antibodies to antagonize the corresponding lymphocyte subsets before radiotherapy to evaluate the contribution of different immune cells to the anti-tumor effects of RT." (PMID 39736508, 2024). "HLA DR is considered essential for initiating autoimmune reactions, and low HLA DR expression may reduce CD4 T cell-mediated anti-tumor immunity." (PMID 39020276, 2024). "Additionally, the MDM2 inhibitor Nutlin-3 was found to enhance antitumor responses of MDM2-specific T cells by upregulating human leukocyte antigen (HLA) class II expression on tumor cells with the aid of CD4 + T cells." (PMID 38281981, 2024). "In our investigation, we observed that the “hot” tumor immune infiltration status predicted by MPIGs manifests as a tumor microenvironment primarily characterized by differential immune cell populations, including CD4+ T cells, B cells, and macrophages." (PMID 38696324, 2024). "IL-6 has been shown to inhibit the differentiation of T cells into Th1 cells, which are central to specific cytotoxic anti-tumor immunity; and to promote the differentiation of CD4 + T cells into Th2 and Th17 cells, which are less effective at controlling tumor growth." (PMID 38689325, 2024). "In mesothelioma mice treated with copper‐lowering therapy, CD4+ T cells may exert anti‐tumour immunity through the specific adhesion molecule CD40 into tumour tissues." (PMID 38801402, 2024).
tumor (continued). "We discovered that the antitumor immune system was promoted in MOC1CX3CL1 tumors, as demonstrated by recruitment of a higher number of cytotoxic T cells, alongside simulation of the pro-tumor immune system in MOC2CX3CL1 tumors when CD4+ T cells and Treg cells are recruited." (PMID 38775151, 2024). "Evaluation of the inferred regulatory functions between immune cells relative to the tumour suggested that macrophages exhibit an immunosuppressive phenotype against both CD4+ and CD8+ T cells, and that this association scores more highly in ICI refractory patients." (PMID 38439077, 2024). "The results showed a significant positive correlation between TLS density and tumor‐infiltrating CD4+ T cells, CD8+ T cells, CD20+ B cells and CD45RO+ memory T cells (Spearman coefficient (ρ) = 0.464, 0.486, 0.431 and 0.348; P < 0.001, < 0.001, < 0.001 and = 0.003, respectively)." (PMID 38322490, 2024). "Research has found that Th1-type cell-directed CD4+ T cells reprogram bone marrow cells of the tumor to express interferon-activated antigen presentation and iNOS-mediated tumor-killing phenotype, thereby inducing the immune-escape tumor to undergo inflammatory cell death." (PMID 38999959, 2024). "In LUAD and LUSC, NCAPD2 expression was not only positively correlated with CD4 + T cells, but also Th2 cells, which may imply that the ratio of Th1 cells to Th2 cells in CD4 + T cells is unbalanced, thus promoting tumor growth." (PMID 38172945, 2024). "M1 macrophages could present neoantigens derived from tumor cells toward CD4+ type I T helper cells (Th1) via HLA-DR (MHC II) receptors, which in turn activate CD8+ cytotoxic T cells." (PMID 39191486, 2024). "Downregulation of CD3/CD4 expression in the tumor and stroma is related to pCR." (PMID 38888366, 2024). "Because of the high TMB of MMRd tumors, it could be that neoantigens are also presented in the context of MHC-II, activating potent CD4+ T cell anti-tumor immunity." (PMID 39544936, 2024). "CD4+ T cells can kill tumor cells through HLA class II molecules presented by tumor cells or APCs." (PMID 38412034, 2024). "Tregs, a specific subset of CD4 T cells, are present in the thymus or peripheral blood, and they facilitate tumor growth within the TME by suppressing the immune response against colorectal cancer (CRC) through direct cellular interactions or cytokine and metabolite release." (PMID 38785789, 2024). "The tumor-infiltration of CD4+ T-cells in TIME is complicated." (PMID 38649887, 2024). "The adaptive anti-tumor immune response relies primarily on CD4+ and CD8+ T cells." (PMID 38675231, 2024). "Interestingly, PRMT3-OE led to a small but significant increase in the tumor volumes and weights and a decrease in T cell infiltration (CD4+, CD8+, and IFNγ+ and GZMB+ CD8+ T cells) in HSP60-R446K OE cells compared to vector control." (PMID 39256398, 2024). "In fact, in vivo NK depletion was shown to abrogate the anti-tumor properties of sFKN, and CD4 and CD8 T-cell depletion also contributed to therapeutic efficacy in a mouse model of lung cancer, although these results were obtained in combination with anti-PD-1 immunotherapy." (PMID 39125578, 2024). "Studies have shown that activated CD8+ and CD4+ T cells boost anti-tumor immunity." (PMID 38900244, 2024). "Based on the concept of tumor immunoediting, we hypothesized that at D23 it is in the equilibrium/evasion phases, justifying the proximity between the phenotypes of CD4+ T lymphocytes and the naive moment." (PMID 38690280, 2024). "cDC2 is vital for priming anti-tumor CD4+ T cells in multiple tumor models." (PMID 38927916, 2024). "CD4, a co-receptor expressed on T-helper cells, monocytes, macrophages, and dendritic cells (DC), thus is positioned to be a key molecule to propagate optimal anti-tumor activity on several levels." (PMID 38386171, 2024).
tumor (continued). "Moreover, CD8+ and CD4+ T-cell densities in the tumour were identified as the two most optimised predictive biomarkers, consistent with observations by studies on single-agent PD-L1 blockade therapies." (PMID 38399453, 2024). "While we did not observe the same skewing of macrophages toward M1 TAMs or more mature DCs in our BPR model, we did note an increase in cytotoxic Granzyme B+ CD4+ T cells known to mediate direct killing of MHC II+ tumor cells, as well as an increase in central memory CD4+ and CD8+ TIL." (PMID 38312842, 2024). "The tumor tissues were subjected to immunohistochemical staining for CD4 and CD8." (PMID 39766327, 2024). "The expression of HAVCR2 is significantly increased on infiltrating tumor tissues of CD4+ and CD8+ T cells, which may play an important role in progression, invasion, and metastasis." (PMID 39640777, 2024). "However, when we analyzed IL2 production by CD8+ T cells and CD4+ Tconv cells, we found that FS120m induced marginally increased expression among cells from the spleen and tumor-draining lymph nodes." (PMID 38995700, 2024). "As for the stroma, MHC-II expression on tumor cells was associated with the presence of high total immune cells (p=0.026) and high CD4+ TH (p=0.026), but not with CD8+ CTL (p=0.072) and CD68+ cells (p=0.062)." (PMID 39035008, 2024). "Moreover, in a subcutaneous transplantation tumor mouse model, the depletion of CD4+ T cells in mice using anti-CD4 Ab alongside anti-CD47 Ab therapy significantly diminished the effect of anti-CD47 Ab in promoting tumor vascular normalization." (PMID 38398223, 2024). "The convergence of these results emphasizes the interplay between tumor cell proliferation and immune responses, underscoring the potential for therapeutic strategies that leverage CD4+ T cells to enhance anti-tumor immunity while targeting key cell cycle regulators such as PLK1, CDK1, and CDC20." (PMID 39457373, 2024). "Moreover, significant correlation between PD-L1 CPS and the number of tumour-infiltrating CD4+ T cells (r = 0.280, p = 0.017) was detected." (PMID 38541208, 2024). "The observed increased localization of CD4+ T cells at the tumor margin in the group receiving Qβ-HPVag might be attributed again to the specific time point at which these tumors were collected." (PMID 38523774, 2024). "However, Tregs, a highly immunosuppressive fraction of CD4+ T cells, have been shown to suppress tumour‐specific immune responses by reducing the infiltration and antitumour activity of CD8+ T cells and macrophages." (PMID 38997802, 2024). "Finally, CD4+ T cells can also become cytotoxic and kill tumor cells directly, demonstrating their important role in the immune response to AML." (PMID 38724673, 2024). "Finally, the same treatment abrogated CD4+CD25+Foxp3+ Treg percentage in the tumor, opening the space for reestablishment of active antitumor immune response." (PMID 38920557, 2024). "CD4+ T cells are required for nearly all functions in tumor immunity." (PMID 38172491, 2024). "In summary, our data demonstrate that EC‐ACKR1 and EC‐KDR‐IGFBP3 possess key characteristics of IMECs, and are involved in antigen presentation processes that specifically drive tumor‐specific immune responses, primarily for the recruitment of functional CD4+ T cells within the tumor." (PMID 38874280, 2024). "An increasing amount of data suggests that tumor-infiltrating CD4+ and CD8+ T cells may be a prognostic biomarker in various cancers." (PMID 38166889, 2024). "Additionally, lactic acid promotes the metabolism of tryptophan and L-kynurenine generation in pDCs, facilitating the development of significant immunosuppressive immune cell groups in the tumor microenvironment, specifically FoxP3+CD4+Tregs." (PMID 39678492, 2024). "The growth rate of tumor in mice being injected aPD-1-PLTM-HMSNs@Sora was slow, which might be associated with a markedly growth of the absolute number of CD4+ and CD8+ T cells in TME." (PMID 38409035, 2024).
tumor (continued). "Moreover, tumor-infiltrating immune cells analysis showed that whole or myeloid Ffar2 gene deletion markedly reduce MDSCs accumulation, but increases CD4+ and CD8+ T cell infiltration in tumors." (PMID 38402237, 2024). "Interestingly, the peripheral CD4+ T cells were contrary to the results of tumor-derived CD4+ T cells in terms of their surface molecules." (PMID 38343544, 2024). "These MDSCs effectively suppress the anti-tumor function of CD4+ and CD8+ T cells." (PMID 38533507, 2024). "This may be because there was not considerable variation in intensity across ROIs for tumor-immune cells, tumor-CD4 T cells, and tumor-CD8 T cells." (PMID 39428129, 2024). "One mechanism involves the engulfment of tumor-derived material followed by the presentation of major histocompatibility complex (MHC) class II (MHCII)-loaded peptides to CD4+ T helper cells, which in turn engage other immune cells such as macrophages and B cells." (PMID 37996514, 2024). "In addition, the anti-CD4 mAb targets both conventional CD4+ T cells as well as T regulatory cells (Tregs), which will reduce tumor growth by itself." (PMID 38523774, 2024). "A recent report revealed that vascular normalization and immunostimulatory reprogramming might regulate each other, highlighting the key role of infiltrating CD4 T cells in promoting tumor vascular normalization." (PMID 38398223, 2024). "In bladder cancer, CD19+ tumour‐infiltrating B cells may activate CD4+ T cells through antigen presentation, thereby improving outcomes with platinum‐based chemotherapy." (PMID 38997802, 2024). "Besides elucidating the role of IFITM3 in Tregs, we also detected the IFITM3 expression in tumor-infiltrating CD4+ and CD8+ T cells to check its potential functions." (PMID 38167862, 2024). "Notably, FOXP3, a transcription factor in Tregs, plays a crucial role in regulating the metabolism and survival of tumor-infiltrating CD4+ CD25+ Tregs in a lactate-rich environment." (PMID 39227970, 2024). "Previous reports had found that MHC-II expressed by tumor cells could directly present endogenous antigens to CD4+T cells and might through endocytosis." (PMID 39105803, 2024). "It was found that the mannan-decorated lipid calcium phosphate nanoparticle vaccine can significantly increase the amount of CD8+ T-cell infiltration in tumor tissues, improve the ratio of CD8+/CD4+ T cells, and promote the transformation of the tumor immune microenvironment." (PMID 39194667, 2024). "Furthermore, the tumor microenvironment (TME) displayed robust expression of CD4+ T lymphocytes and PD-1, whereas the distribution of CD8+ T lymphocytes and PDL-1 was sporadic." (PMID 38283145, 2024). "Accordingly, a high percent of CD4+ T cells in the tumor microenvironment may predict poor prognosis in NSCLC, and cytotoxic Th1 cells and dendritic cells can maintain anti-tumor immunity." (PMID 38261568, 2024). "At the endpoint (week 7), upon sequential PD-L1 and IL-6R immunotherapy, splenic lymphocytes of the shMCT-1 tumor-bearing mice increased more CD4(+) helper T cells and CD19(+) B cells but unchanged CD8(+) CTLs and NK cells when compared with those bearing scramble tumors and treated by isotype IgG." (PMID 38505617, 2024). "Some studies in mice and humans suggested cDC2s may also play a pro-tumor/immunosuppressive role by preventing CD4+ effector T cell function or correlating with Tregs and an exhausted T cell population." (PMID 38261139, 2024). "CD4+ T cells were comprehensively found in greater proportions in tumor populations, with CD4+ central memory (Tcm) (Diff = 7.2%, p = 0.031), FOXP3+ T regulatory (Treg) (Diff = 7.6%, p = 0.035), Naive CD4+ (Diff = 13.2%, p = 0.0021), and T helper 2 (Th2) (Diff = 3.6%, p = 0.0059) all enriched." (PMID 39075108, 2024).
tumor (continued). "CD4+ and CD8+ T cells recognize peptide tumor antigens presented by antigen presenting cells and undergo activation, proliferation, and differentiation into CD4+ T follicular helper (TFH) cells and CD8+ effector memory cytotoxic cells which often represent the dominant subsets." (PMID 38426109, 2024). "Additionally, tumor cells exhibit immunosuppressive properties, inhibiting CD4 T-cell proliferation in vitro." (PMID 39123357, 2024). "Anti-tumoral immunity is accomplished in this setting both through innate mechanisms with dendritic and NK cell inflammatory activation and through adaptive mechanisms involving CD4+ and CD8+ responses following the release of tumor-associated antigens from infected and lysed tumor cells." (PMID 38398094, 2024). "IL-6 may inhibit anti-tumor immunity through effects on CD4+ T cell differentiation and CD8+ T cell cytotoxicity." (PMID 39088539, 2024). "In addition, many cancers have tumor-infiltrating M1 and M2 macrophages, neutrophils (Neu), CD4+ T cells (T-helper), CD8+ T cells (T-cytotoxic), eosinophils, and mast cells." (PMID 38730579, 2024). "To identify whether the knockdown of Aurora-A can influence the cytotoxic activity of tumor-infiltrating T cells, we analyzed IFNγ+/CD4+, IFNγ+/CD8+, and TNFα+/CD8+ T cell populations in tumors." (PMID 38291041, 2024). "Additionally, lowering copper levels in tumour tissues has been shown to enhance the ability of CD4+ T cells to target and eradicate tumours." (PMID 38801402, 2024). "In addition to CD8 + T cells, CD4 + T cells also involve in the tumor immune microenvironment by activating and regulating the functions of other immune cells such as CD8 + T cells and macrophages." (PMID 38720149, 2024). "Additionally, NAPSL.p@OVA induced a significant increase in tumor-specific interferon-γ (IFN-γ) secreting CD4+ and CD8+ T cells." (PMID 38764014, 2024). "Further database analysis using different algorithms (TIMER2.0) revealed that TGFBR1 gene expression displayed more significant positive correlations with infiltrating macrophages than with other infiltrating immune cell types (B cells, CD8+ T cells, and CD4+ T cells) in various human tumor types." (PMID 38441961, 2024). "In one preclinical cDC1 diphtheria toxin receptor (DTR) knockout model, intratumoral regulatory T cell (Treg) depletion enhanced cDC2 migration to the tumor-draining lymph node and reversed dysfunction, leading to productive priming and activation of effector CD4 T cells." (PMID 38903502, 2024). "Emerging evidence in different models indicates that CD4+ T cells may play a role in anti-tumor immunity, distinct from their conventional function as helpers and regulators of cytotoxic CD8+ T cells." (PMID 39544936, 2024). "Importantly, neoantigen-specific CD4+ T cells are capable of producing Th1 cytokines, eradicating irradiated tumor cells, and facilitating epitope spreading." (PMID 39507526, 2024). "Thus, the balance between pro-tumor and anti-tumor activities of CD4+ T cells plays a critical role in shaping the immune landscape of the TME." (PMID 38649887, 2024). "CD4+ T helper (Th) cells play a crucial auxiliary role in tumor immunity." (PMID 38887597, 2024). "Tumor-infiltrating NK cells are associated with Tregs, and an increase in CD4+ CD25+ Tregs may impair the ability of tumor-infiltrating NK cells to produce IFN-γ and eliminate K562 targets, thereby affecting their anti-tumor efficacy." (PMID 38426090, 2024). "CD4(+) T cells expressing IL-17 and IL-21 constituted less than 0.89 ± 0.11% of all cytokine-producing CD4(+) T cells, indicating minimal involvement of Th17 and T- follicular helper (Tfh) in the tumor microenvironment." (PMID 38895115, 2024). "Injection of an anti-CD20 monoclonal antibody might in this case eliminate the anti-CD4 CAR T cells as well as mature B cells, which are part of the tumor microenvironment and are important for the survival of the malignant CD4 T cells." (PMID 39272178, 2024).